TRPC6 (transient receptor potential cation channel subfamily C member 6)
Diseases named in the same sentence as TRPC6 in open-access papers (continued):
Sharing a sentence is not in itself a finding about the gene and the disease.
Hyperglycemia (23 papers, 2013 to 2025). An increased concentration of glucose in the blood. "Hyperglycemia is also associated with TRPC6 and NFAT upregulation in kidney, monocytes, and platelets." (PMID 36936781, 2023). "Hyperglycemia and elevation in angiotensin II (Ang II) levels are sufficient to cause overexpression of TRPC6, resulting in increased calcium influx and eventual podocyte dysfunction and death." (PMID 37675019, 2022). "Our initial impetus for exploring O-GlcNAcylation of TRPC6 was triggered a hypothesis that this PTM might be linked to NFAT activation by hyperglycemia (HG)." (PMID 36936781, 2023). "Our data also suggest that TRPC6 may contribute to the development of renal injury associated with activation of the apoptosis pathway when hyperglycemia and high BP coexist." (PMID 34866402, 2022). "In respect of Szrejder’s study, metformin appears to normalize this signaling pathway by reducing TRPC6 expression in podocytes in hyperglycemia." (PMID 37685845, 2023). "TRPC6 is activated by hyperglycemia in renal resident cells in DN, including tubular cells, podocytes, and mesangial cells, while inhibiting TRPC6 expression or activity can delay DN progression." (PMID 35480629, 2022). "Consistent with previous reports, we found that calpain activity was upregulated in podocytes under hyperglycemia, which was abolished by TRPC6 inhibition." (PMID 36213244, 2022). "Taken together, we show that hyperglycemia only slightly impairs cognitive function but that RH significantly promotes the progression of AD by inhibiting TRPC6/GLUT3-mediated glucose uptake in APP/PS1-DM mice." (PMID 35077394, 2022). "Overall, mild type 1 DM in WT and TRPC6 KO mice were created with similar hyperglycemia and metabolic phenotypes when measured before and after the AC or sham surgery." (PMID 34866402, 2022). "Deletion of TRPC6 markedly attenuated renal dysfunction and reduced apoptotic cell injury in glomeruli and tubules of kidneys exposed to hyperglycemia and high BP." (PMID 34866402, 2022). "In mice with TRPC6 deficiency, the renal dysfunction, albuminuria, glomerular injury, and apoptosis in kidneys exposed to both HTN and hyperglycemia were greatly attenuated." (PMID 34866402, 2022). "In summary, our research demonstrated that KL defended against hyperglycemia-induced podocyte injury in DN via suppressing TRPC6, which provided novel mechanistic insights for the role of KL in DN." (PMID 35480629, 2022). "Even though the kidneys of TRPC6 KO mice were exposed to similar hyperglycemia and high BP, they had much less injury than observed in WT mice." (PMID 34866402, 2022). "Further experiments suggested that NFATc1 siRNA mimicked the effect of TAC, whereas transfection of the TRPC6 overexpression plasmid blocked the effect of TAC on tubular inflammation under hyperglycaemia." (PMID 32779844, 2020). "Specifically, STZ‐induced hyperglycemia significantly upregulated TRPC6 expression, whereas RH specifically inhibited TRPC6 expression in DM mice but not in nondiabetic (ND) controls." (PMID 33135341, 2020). "TRPC6 interaction with TRPC3-NOX2 protein complex attenuates the hyperglycemia-induced heart failure in mice." (PMID 31871548, 2019). "Hyperglycemia-induced intracellular calcium overload activates calcium-dependent proteases (e.g., calpain) and TRPC6 channels, leading to mesangial extracellular matrix deposition and podocyte cytoskeletal collapse, which exacerbate proteinuria and glomerulosclerosis." (PMID 40641971, 2025). "Moreover, metformin normalized TRPC6 expression via AMPKα1 activation in podocytes exposed to hyperglycemia." (PMID 37685845, 2023). "Based on our data, attenuation of podocyte injury may be associated with reducing hyperglycemia, upregulation of SOD-1/SOD-3 mRNA expression, and downregulation of the TRPC6 mRNA expression in the CeA treatment in early hyperglycemia condition." (PMID 34326888, 2021).
Hyperglycemia (continued). "We further examined whether TRPC6 negatively regulates hyperglycemia-induced inflammatory cytokine production in NRCMs." (PMID 28790356, 2017). "Furthermore, the incidence of TRPC6 in patches was higher in the podocytes subject to hyperglycemia (45.5% of patches on STZ-treated animals compared to 19.6% in control)." (PMID 26656101, 2015). "Despite high clinical utility of cilostazol, its underlying mechanism is an indirect inhibition of TRPC6 channel activity and endogenous activity of phosphorylating TRPC6 in VSMCs which could be decreased by various environmental changes, including endothelial dysfunction, hyperglycaemia and ageing." (PMID 36068079, 2023). "On the other hand, the upregulation of the TRPC6 protein destabilizes the TRPC3-Nox2 complex and prevents hyperglycemia-induced ROS generation-dependent cardiac dysfunction." (PMID 38397074, 2024). "In contrast, GFR in the right kidneys of TRPC6 KO DM + AC mice was preserved, despite being exposed to HTN and hyperglycemia, and had similar values as in the left kidneys of the same DM + AC mice and in the right kidneys of DM mice." (PMID 34866402, 2022). "In conclusion, this study delineated that TAC has a potential effect on the amelioration of tubuloinflammation and fibrosis, partially through NFATc1/TRPC6, which provides more evidence for the renoprotective effects of TAC under hyperglycaemia." (PMID 32779844, 2020). "Upregulation of TRPC6 protein destabilizes the TRPC3-Nox2 complex, which leads to prevention of ROS production-dependent cardiac dysfunction induced by hyperglycemia." (PMID 28790356, 2017). "In the present study, we determined 1) whether hyperglycemia in type 1 DM and moderate HTN synergistically promote kidney injury and 2) whether TRPC6 plays a role in contributing to kidney injury induced by the combination of DM and HTN." (PMID 34866402, 2022). "TRPC6 KO mice, however, were protected from the synergistic impact of DM and HTN to promote albuminuria, glomerular injury, and apoptosis in kidneys exposed to similar levels of hyperglycemia and elevated BP as in WT mice." (PMID 34866402, 2022). "Hyperglycemia induced by STZ significantly increased mRNA expression level of TRPC6, but not that of TRPC3, in mouse heart." (PMID 28790356, 2017). "Given this, there may be conditions, for example during hyperglycemia or when glomerular hypertension is already well developed, when inhibition of 20-HETE synthesis or its actions on TRPC6 could be beneficial." (PMID 27630573, 2016). "Hyperglycemia, at 21 days, also increased protein expression of cystathionine-β-synthase enzyme (CBS) and TRPC6, but not TRPA1 nor TRPV1, channels in dorsal root ganglia (DRG)." (PMID 30602386, 2019).
hepatocellular carcinoma (22 papers, 2009 to 2024). A malignant tumor that arises from hepatocytes. "A subtype of TRPC6 has also been implicated in another malignancy infamously recalcitrant to multiple chemotherapeutic regimens, hepatocellular carcinoma (HCC)." (PMID 29636894, 2018). "Hypoxia upregulated TRPC6 mRNA expression in hepatocellular carcinoma cells, where TRPC6-mediated Ca2+ influx conferred drug resistance to these cells via the Ca2+-dependent STAT3 signalling pathway in hypoxic conditions." (PMID 35806388, 2022). "TRPC6 is weakly expressed on mRNA and protein level in normal hepatocytes but strongly expressed in liver carcinoma samples." (PMID 32182937, 2020). "It was also described that TRPC6 channels in Human Hepatocellular Carcinoma Cells are involved in migration and invasion in response to TGF-β115." (PMID 32350291, 2020). "In hepatocellular carcinoma cells, TRPC6 is a negative regulator of cell death induced by doxorubicin, hypoxia, and ionizing radiation." (PMID 31189890, 2019). "TRPC6 has been suggested to play a role in hepatoma cell-line proliferation, possibly via a cyclin D-modulated mechanism." (PMID 28062682, 2017). "TRPC1 and TRPC6 have convincingly linked to SOCE in a growing number of human tumours, including breast carcinoma, glioblastoma multiforme (GBM), and hepatoma." (PMID 25126575, 2014). "Moreover, in human hepatoma cell line Huh-7, it has been also shown that Ca2+ entry involving TRPC6, together with STIM1 and Orai1, increases cyclin D1 expression." (PMID 24058448, 2013). "Similarly, TRPC6 was induced by doxorubicin treatment in Huh7 and HepG2 hepatocellular carcinoma cells, therefore its inhibition enhanced doxorubicin-induced cell death, suggesting that high TRPC6 level is associated with chemoresistance in hepatocarcinoma cell lines." (PMID 32575381, 2020). "The expressions of both TRPC6 and NCX1 are markedly increased in human hepatocellular carcinoma tissues, and their expression levels positively correlate with migration, invasion, and intrahepatic metastasis." (PMID 37892239, 2023). "TRPC6 is also a member of the transient receptor potential (TRP) channel superfamily and promotes the development of multidrug resistance in hepatocellular carcinoma (HCC)." (PMID 36187789, 2022). "Recent study indicates that over-expression of TRPC6 regulated multi-drug resistance (MDR) by elevation of intracellular calcium under hypoxia, or stimuli of doxorubicin and ionizing radiation in hepatocellular carcinoma." (PMID 36033489, 2022). "The TRPC6 channel is overexpressed in hepatocellular carcinoma (HCC) cells, where it may promote the sustained accumulation of intracellular calcium that influences multidrug resistance processes." (PMID 35207698, 2022). "In particular, TRPC6 and TRPV6 have recently been reported to play a critical role in the development of many carcinomas including human hepatocellular carcinoma, renal cell carcinoma, prostate cancer, lung cancer, and other types of cancer." (PMID 31627357, 2019). "First, endogenous TRPC6 mediates SOCE and sustains proliferation in Hep G2 and Huh-7 human hepatoma cells, in human and rat glioma cell lines and in human gastric cancer cells." (PMID 25126575, 2014). "Finally in liver tumor samples TRPC6 was expressed more strongly than in isolated hepatocytes from healthy patients and experiments suggested that TRPC6 may play a role in control of human hepatoma cell proliferation." (PMID 19689790, 2009). "TRPC6 and TRPV2 may contribute to the progression of hepatocellular carcinoma, which may be related to the stemness of hepatocellular carcinoma, migration, and the invasion of hepatocellular carcinoma cells." (PMID 38255767, 2024). "Knockdown of TRPC6 by siRNA can attenuate SOCE and proliferation rate in human hepatoma cells." (PMID 25365342, 2014). "Third, TRPC6 is sensitive to CAI in Hep G2 and Huh-7 human hepatoma cells, albeit this drug may also prevent intracellular Ca2+ mobilization in mRCC cells." (PMID 25126575, 2014).
hepatocellular carcinoma (continued). "In human hepatocellular carcinoma cells, transforming growth factor beta (TGFβ) is a mediator of motility, invasion, and metastases via the stimulation of Na+/Ca2+ exchanger 1 (NCX1), and TRPC6 activation regulates TGFβ, thus inducing the formation of a TRPC6/NCX1 molecular complex." (PMID 37892239, 2023). "In line with this, the inhibition of TRPC6 with its specific blocker SKF-96365 or with siRNA reverted doxorubicin-induced epithelial-mesenchymal transition, hypoxia-induced Hif1- α expression and inhibit DNA damage, thereby attenuating drug resistance in hepatocellular carcinoma cells." (PMID 35207698, 2022). "Interestingly, TGF-β induces intracellular release of Ca2+ ion in human hepatoma cells, by increasing the expression levels of Na+/Ca2+ exchanger 1 (NCX1) and the canonical transient receptor potential channel 6 (TRPC6), in addition to enhancing the NCX1-TRPC6 interaction." (PMID 31614569, 2019).
glioma (19 papers, 2011 to 2023). A benign or malignant brain and spinal cord tumor that arises from glial cells (astrocytes, oligodendrocytes, ependymal cells). "It has also been shown that inhibition of TRPC6 channels causes the cell cycle of oesophageal cancer, glioma, and renal carcinoma cells arrested at the G2/M phase." (PMID 28030826, 2017). "The Ca2+-permeable transient receptor potential canonical channel protein 6 (TRPC6) has been implicated in glioma proliferation." (PMID 22389824, 2011). "Indeed, the inhibition/silencing of TRPC6 was associated with a reduction in glioma growth, invasion and angiogenesis." (PMID 33928077, 2021). "An accelerated G2 phase progression may lead to an impaired DNA damage checkpoint and thus to an enhanced genomic instability, explaining the TRPC6 association with enhanced glioma cell malignancy." (PMID 33928077, 2021). "Another member of the TRPC subfamily specifically implicated in glioma progression is TRPC6." (PMID 33928077, 2021). "Recent reports have found that hypoxia in glioma cells led to the activation of transient receptor potential canonical 6 (TRPC6) channels by the IGF-1R-PLCγ-IP3R pathway." (PMID 36768856, 2023). "Studies performed in U251MG and U87MG glioma cell lines revealed that TRPC6 influenced the stability of HIF-1α by controlling its hydroxylation." (PMID 36768856, 2023). "Higher levels of TRPC4, TRPC6, MCOLN1, MCOLN2, and MCOLN3 were significantly associated with shorter OS times in glioma." (PMID 35625048, 2022). "In our present study, the results showed that the expression of TRPC1 and TRPC3 was significantly increased in glioma with IDH mutation status and 1p/19q codeletion status, while the expression of TRPC6, MCOLN1, MCOLN2, and MCOLN3 was significantly decreased." (PMID 35625048, 2022). "In human glioma cells, attenuation of TRPC6 activity inhibits cell growth and arrests the cell cycle." (PMID 34149360, 2021). "Impairing TRPC6 activity in vitro in human glioma cells induced cell cycle arrest at the G2/M phase and, in vivo, reduced human xenograft growth in immunocompromised mice, while increasing the survival of the xenografted mice." (PMID 34458247, 2021). "We found that both the mRNA and protein levels of POX in LN229 human glioma cells were upregulated when TRPC6 activity or expression was inhibited by DNC6 or by RNAi." (PMID 33508123, 2021). "Not only is the TRPC6 channel overexpressed in human glioma cells at both the protein and mRNA levels, as compared to normal glial cells, but also TRPC6 expression relates to the grade of glioma." (PMID 34458247, 2021). "Next, in ∼75% of >40 human glioma samples, the protein expression level of TRPC6 or p21 was ∼3.3- or 3.5-fold higher whereas that of POX or PTEN was ∼6.4- or 1.4-fold lower than in normal tissues." (PMID 33508123, 2021). "Under hypoxia, TRPC6 channels also control in vitro hydroxylation and stability of hypoxia inducible factor-1 alpha in human glioma cells." (PMID 34458247, 2021). "Here, we discuss the potential as biological markers of diagnosis and prognosis of TRPC6, TRPM8, TRPV4, or TRPV1/V2 being associated with glioma patient overall survival." (PMID 33928077, 2021). "One of the most studied TRPC6-related roles in cerebral pathologies is in the development and progression of gliomas." (PMID 33240883, 2020).
glioma (continued). "Although there are several possible mechanisms for TRPC6-mediated regulation of the RhoA/Rock pathway in glioma progression, this still needs to be confirmed in the context of this neoplastic disease." (PMID 33240883, 2020). "RhoA activity can promote the activation of FAK, suggesting an additional mechanism for TRPC6-RhoA mediated tumoral progress in glioma." (PMID 33240883, 2020). "Activated TRPC6 stabilizes HIF-1α in hypoxic glioma cells and supports hypoxic glucose metabolism of cancer cells via the GLUT1 transporter." (PMID 29772843, 2018). "In glioma cells, TRPC6 is upregulated and required for the hypoxia-mediated increase in proliferation and cell invasion." (PMID 29772843, 2018). "Recent studies have shown that in human oesophageal cancer and glioma cells, inhibition of TRPC6 induces cell cycle arrested at the G2/M phase." (PMID 28030826, 2017). "Silencing of TRPC6 reduces proliferation of some esophageal and breast cancer cell lines and glioma cells." (PMID 25852478, 2015). "Knockdown of TRPC6 expression inhibits glioma growth, invasion, and angiogenesis, and is an important mediator of glioblastoma tumor growth in vitro and in vivo." (PMID 25852478, 2015). "TRPC6 was shown to be required for the development of the aggressive tumor phenotype, because a knockdown of the TRPC6 inhibited the glioma growth, invasion, and angiogenesis." (PMID 25866806, 2015). "Inhibition of TRPC6 activity showed reduced glioma cell growth, G2 phase cell cycle arrest, and reduced growth of subcutaneously and intracranially implanted gliomas, as well as increased survival of mice in vivo." (PMID 25852478, 2015). "The hypoxia-induced TRPC6 upregulation is required for the development of the aggressive phenotype as TRPC6 knock-down inhibited glioma growth, invasion, and angiogenesis." (PMID 25642170, 2014). "Both pharmacological inhibition of Notch and knockdown of TRPC6 expression reduce in a similar way glioma migration and invasion in vitro." (PMID 24204345, 2013). "Another candidate gene on 11q22 is TRPC6, as suggested by two recent studies which reported overexpression of TRPC6 in glioma and glioblastoma multiforme (GBM) and analyzed its functional importance in cell growth, proliferation and increased radioresistance." (PMID 21386901, 2011). "TRPC6 is overexpressed in human glioma cells, and inhibition suppressed intracellular [Ca2+] and cell growth and induced cell cycle arrest at the G2/M phase." (PMID 22389824, 2011). "TRPC6 is the only TRP channel shown to be involved in glioma angiogenesis." (PMID 36768856, 2023). "Blocking TRPC6 or NFAT under hypoxic conditions reduced glioma cell line proliferation." (PMID 36768856, 2023). "TRPC6 enhances cell proliferation, tumor growth, and angiogenesis, which is essential for glioma." (PMID 35625048, 2022). "Among the eight final identified hub genes, higher expression levels of TRPC1, TRPC3, and TRPC5 were significantly associated with longer OS time in glioma, while higher expression levels of TRPC4, TRPC6, MCOLN1, MCOLN2, MCOLN3 were significantly associated with shorter OS time." (PMID 35625048, 2022). "Impairing TRPC6 activity in human glioma cells could reduce human xenograft growth in immunocompromised mice." (PMID 35625048, 2022). "TRPC6 is a channel protein important for cancer devolvement and human glioma cell proliferation." (PMID 33508123, 2021). "TRPC6 is overexpressed in glioma samples compared to normal brain tissue." (PMID 33240883, 2020). "Moreover, TRPC6 maintains the stability of HIF-1α in glioma cells under hypoxia and mediates Notch-Driven glioblastoma growth and invasiveness." (PMID 33240883, 2020).